YTHDF1 (YTH N6-methyladenosine RNA binding protein F1)
Diseases named in the same sentence as YTHDF1 in open-access papers (continued):
Sharing a sentence is not in itself a finding about the gene and the disease.
cancer (continued). "This suggests that YTHDF1 may have different effects in the treatment of different tumors, and may be used as a target in the future to improve the effect of cancer treatment according to its role in different tumors." (PMID 39033180, 2024). "Therefore, future elucidation of the roles of YTHDF1 in various immune and cancer cells will be important in the context of the antitumor effects of IR." (PMID 39325547, 2024). "YTHDF1 has been found to play a crucial role in translation regulation in various cancers." (PMID 38444581, 2024). "For example, YTHDF1 often exhibits cancer-promoting effects in tumors." (PMID 39303913, 2024). "Moreover, we found that YTHDF1 was expressed abnormally in a number of cancers, primarily in an overexpressed form." (PMID 38339157, 2024). "Furthermore, the knockdown of YTHDF1 rendered cancer cells resistant to cisplatin treatment via the Keap1-Nrf2-AKR1C1 axis in NSCLC." (PMID 36650570, 2023). "The possible prognostic value of YTHDF1 in various cancers were reviewed as follows." (PMID 36707507, 2023). "YTHDF1 enhanced the proliferation and cancer stem cell-like properties of glioblastoma cells." (PMID 36835633, 2023). "Therefore, as described in this review, because of its crucial role in human progression it will be extremely important to develop small molecule inhibitors of YTHDF1 or screen natural compounds that can down-regulation YTHDF1 for cancer treatment." (PMID 36650570, 2023). "Screening for potential post-transcriptional regulations revealed that the cancer variant falls within the target binding regions of six RBPs, including the m6A reader YTHDF1, which is known to bind m6A-containing RNAs and promote cancer stem cell properties of GBM cells." (PMID 36096444, 2023). "Therefore we focus on some relevant aspects of the regulatory role played by YTHDF1 as gene expression, complex cell networking: stem cell self-renewal, embryonic development, and human cancers progression." (PMID 36650570, 2023). "Finally, we analyzed the expression of YTHDF1 in the TCGA pan-cancer database and found that it was highly expressed in a variety of tumors." (PMID 37108067, 2023). "The copy number gain and amplification were highly increased in various human cancers, which might contribute to the upregulation of YTHDF1 in cancers." (PMID 36707507, 2023). "Moreover, the METTL3–Snail–YTHDF1 axis can promote metastasis in malignant tumors with the modification of EMT-related mRNAs mediated by m6As, which leads to progression." (PMID 36675186, 2023). "YTHDF1 is found to regulate cancer stem cell(CSC)-like characteristic." (PMID 36707507, 2023). "We further explored progress-free survival (PFS), and interestingly, we found that YTHDF1/2 was a risk factor for cancer progress in KICH, LIHC and PRAD, while YTHDF3 was a risk factor for cancer progress in KICH and KIRP, and a protective factor in KIRC and LUSC." (PMID 37833468, 2023). "Thus, as a core factor in m6A modification, YTHDF1 possessed a global effects to target and regulate multiple genes in human cancer progression." (PMID 36707507, 2023). "Emerging work has shown that YTHDF1 plays an important role in cancer chemoresistance." (PMID 36650570, 2023). "The regulatory mechanism of YTHDF1 in human cancers were demonstrated in several cancers." (PMID 36707507, 2023). "For example, STAU1 and YTHDF1 were highly altered across stages in both carcinomas." (PMID 37384253, 2023). "Previous findings suggest that YTHDF1 or YTHDF2 may be a therapeutic target for cancer immunotherapy or a predictive biomarker predicting the response to anti-PD-1/PD-L1." (PMID 36479088, 2022). "Clinical evidence confirms that YTHDF1 is commonly up-regulated in many cancers and could maintain hypoxia tolerance by promoting the translation of certain proteins." (PMID 35319018, 2022). "In addition, the Wnt/β-catenin signaling pathway, the m6a “eraser” ALKBH5, and miR-3436 were reported to regulate YTHDF1 expression in cancers." (PMID 35197112, 2022).
cancer (continued). "To further elucidate the function of YTHDF1, we performed pan-cancer analyses of YTHDF1." (PMID 35075167, 2022). "YTHDF1 was considered as a potential cancer biomarker for prognosis and immunotherapy." (PMID 36072430, 2022). "YTHDF3, YTHDC1, and YTHDC2 are less important to cancer than YTHDF1 and YTHDF2." (PMID 36226062, 2022). "Recent evidence indicates that YTHDF1 expression in cancer cells could modify the GC immune microenvironment." (PMID 35884552, 2022). "The results showed that the cancer tissues of 18 samples showed different degrees of elevated expression of YTHDF1 compared with the paracancerous tissues, while the expression level of YTHDF1 in 4 cases was not significantly higher or even lower than that in adjacent tissues." (PMID 35319018, 2022). "Given the highly diverse roles of YTHDF1 in promoting mRNA translation, the therapeutic effects of targeting YTHDF1 may vary in different cancers." (PMID 35884552, 2022). "Moreover, proteins responsible for m6A modification, including writers (such as METTL3/14), erasers (such as FTO and ALKBH5), and readers (such as YTHDF1/2/3), have been found to be overexpressed and promote the initiation and development of many cancer types." (PMID 35986274, 2022). "Only a few previous studies have reported on the relationship between YTHDF1 and cancer." (PMID 36479088, 2022). "YTHDF1 was positively correlated with the DNA and RNA stemness scores in most cancers." (PMID 35075167, 2022). "YTHDF1 coordinates with other m6A regulators to promote cancer progression." (PMID 36291811, 2022). "Finally, we confirmed the role of YTHDF1 as a potential prognostic biomarker through pan-cancer analysis." (PMID 35075167, 2022). "Suppression of YTHDF1 could block proliferation, migration and invasion in OS cell lines and mouse xenograft model, which indicated that targeting YTHDF1 in cancer cells could be an effective therapeutic strategy." (PMID 35156522, 2022). "The GEPIA database analysis showed that YTHDF1 was highly expressed in seven cancers." (PMID 35401696, 2022). "Presently, the study on the role of YTHDF1 in cancers primarily concentrated on promoting m6A-modified mRNA translation, and there are a few studies on other biological functions that YTHDF1 may involve." (PMID 35401696, 2022). "Moreover, studies highlight the key role of m6A in EMT progression, cancer metastasis, and YTHDF1-mediated Snail translation." (PMID 34996459, 2022). "Studies have found that YTHDF1 has a clear oncogenic role, and its high expression in cancer genes can accelerate the transformation of important oncogenic drivers in cancer via numerous methods, impacting cancer progression and prognosis." (PMID 35707365, 2022). "Therein, these results suggest that inhibition of YTHDF1 activity might be used in combination with immune checkpoint inhibitors to enhance the killing of cancer cells by the immune system." (PMID 36012237, 2022). "In TCGA database, cancer tissues expressed higher level of YTHDF1 compared to normal tissues." (PMID 35279688, 2022). "We evaluated m-6-A modified protein, which showed IMPDH1 was closely related to m-6-A related regulatory proteins in pan-cancer, and we focused on evaluating the association of IMPDH1 with the top four proteins: YTHDF1, ALKBH5, YTHDF2, METTL3 in HCC, indicating a strong relationship." (PMID 36618420, 2022). "For example, loss of the lncRNA, THOR, inhibits the proliferation, migration, and invasion of cancer cells in vitro and in vivo, while the m6A readers, YTHDF1 and YTHDF2, can regulate THOR, thereby inhibiting the occurrence and development of tumors in vivo and in vitro." (PMID 35692827, 2022). "The role of YTHDF1 in cancer occurrence and treatment remains controversial." (PMID 33692959, 2021). "In cancer, aberrant reader proteins, such as YTHDF1, could lead to the disorders of RNA metabolism that contributed to tumor progression." (PMID 34745970, 2021).
cancer (continued). "In addition, we also found that inhibition of YTHDF1 decreased the G0/G1 phase and increased S-phase in cancer cells." (PMID 34729106, 2021). "Moreover, recent studies reported that YTHDF1 was involved not only in the glycolysis of cancer cells by promoting mRNA stability of PDK4 but also in cancer drug resistance." (PMID 34745970, 2021). "The role of YTHDF1 was reported in various cancer types, and it plays a critical role in cancer." (PMID 34745970, 2021). "Molecular mechanism experiments revealed that c‐Myc could drive YTHDF1 to facilitate cancer proliferation." (PMID 34151473, 2021). "The expression of the YTHDF1 gene is increased in many cancers, suggesting that the YTHDF1 gene may be an important oncogene." (PMID 34794452, 2021). "However, the role of YTHDF1 in prognosis and immunology in human cancers has seldomly been analyzed systematically." (PMID 34026603, 2021). "After proving the differential YTHDF1 expression in different immune subtypes, we explored the potential correlation between YTHDF1 expression and immune cell infiltration in human cancers, and the results indicated that there was significant correlation in 31 cancer types." (PMID 34026603, 2021). "Our pan-cancer analysis revealed that YTHDF1 was up-regulated in most types of cancer." (PMID 34434939, 2021). "The prognostic value of YTHDF1 expression in human cancers was analyzed by several databases." (PMID 34026603, 2021). "In general, YTHDF1 expression was higher in tumors than in paired normal tissue in human cancers." (PMID 34026603, 2021). "For example, YTHDF1 expression had a strong association with STAT1 in Th1 cells, STAT6 in Th2 cells, STAT3 in Th17 cells, STAT5B in Treg cells, BCL6 in Tfh cells, and IRF5 in M1 macrophages in most cancer types." (PMID 34026603, 2021). "Moveover, YTHDF1 inhibition also increases PD-L1 checkpoint blockade potency in cancer regression." (PMID 34526985, 2021). "Taken together, the current study suggests that YTHDF1 may be harnessed as a new immunotherapeutic target to improve patient outcomes with cancer." (PMID 33692959, 2021). "In ovarian cancer, YTHDF1 promotes cancer progression by enhancing EIF3C translation." (PMID 33816306, 2021). "In addition, in many other cancer types such as ACC, BLCA, MESO, UVM, LIHC, and UCS, high YTHDF1 expression meant worse prognosis, which proved that YTHDF1 was a potential prognostic pan-cancer biomarker." (PMID 34026603, 2021). "Molecular mechanism experiments showed that c-Myc could drive YTHDF1 to promote cancer proliferation." (PMID 32742460, 2020). "Studies have shown that of YTHDF1 silencing inhibits cancer proliferation." (PMID 32709063, 2020). "It was speculated that YTHDF1 might be involved in the regulation of cancer stem cell properties, thereby facilitating HCC progression." (PMID 33363211, 2020). "RNA methyltransferases (such as METTL14, METTL3 and TAP), the demethylases(such as ALKBH5 and FTO), and the binding proteins (such as YTHDF2 and YTHDF1) are often upregulated in a variety of human cancer types to increase the expression of oncogenes and oncoproteins." (PMID 33136551, 2020). "The mechanism of m6A “reader” YTHDF1 in cancer has been extensively researched." (PMID 32934298, 2020). "Furthermore, m6A modified mRNA binding protein YTHDF1, one of evolutionary positively selected genes for high-altitude adaptation is amplified in various cancers, including non-small cell lung cancer (NSCLC)." (PMID 31653849, 2019). "To identify genes that are associated with CRC, we analyzed the expression of YTHDF1 in CRC on online databases The cancer genome atlas (TCGA) and Gene Expression Omnibus (GEO) profiling showed that YTHDF1 is significant upregulated in tumors compared with that in adjacent normal tissues in CRC." (PMID 31131257, 2019).
cancer (continued). "Additionally, The Catalog Of Somatic Mutations In Cancer (COSMIC) showed that among 150 CRC patients with the increase in YTHDF1 expression, 42% (64/150) had an amplification of the YTHDF1 copy number." (PMID 31131257, 2019). "We then studied whether c-Myc was associated with the 5′ region of the transcription start site of the YTHDF1 gene by chromatin immunoprecipitation database (ChIP-atlas) in cancer cells lines." (PMID 29484125, 2018). "Considering that c-Myc is overexpressed in 70% cases with CRC and generates unique transcription networks, which characterizes cancer, this study suggests that c-Myc induces an oncogenic effect on the transactivation of the m6A reader YTHDF1 in an uncharacterized pathway." (PMID 29484125, 2018). "Nevertheless, how YTHDF1 works in the transcription network in cancer is still unclear." (PMID 29484125, 2018). "DC-specific Ythdf1 loss increased type I IFN production, enhanced cross-priming, and potentiated CD8+ killing, improving the efficacy of radiation and combined radiotherapy plus anti-PD-L1 in multiple murine cancers; a prototype DC vaccine built from Ythdf1-deficient DCs amplified these effects." (PMID 41280938, 2025). "We previously highlighted that m6A was critical in the progress of epithelial–mesenchymal transition (EMT) since Snail could be modified by m6A in the CDS region and METTL3/YTHDF1 could mediate the expression and translation of Snail mRNA to regulate cancer cells growth and metastasis." (PMID 36260366, 2023). "Thus, YTHDF1 worked as an effective therapeutic target in immunotherapy in human cancers." (PMID 36707507, 2023). "Thus, how to induce the YTHDF1-mediated ferroptosis of cancer cells might be an effective way for clinical therapy of HNSCCs." (PMID 36707507, 2023). "Therefore, we systematically summarize the recent advances of YTHDF1 in human cancer." (PMID 36650570, 2023). "Thus, YTHDF1 expression shows totally different expression models in distinct cancer." (PMID 35022030, 2022). "Therefore, whether GMEB2 mRNA is regulated by YTHDF1 in an m6A-dependent manner in cancer deserves further investigation." (PMID 36551532, 2022). "Our results show that the cancer-promoting impact of ZNF320 is associated with the modification of m6a, which may influent the mRNA methylation level of HCC through its association with YTHDF1, and finally impact the progress of HCC." (PMID 36287187, 2022). "Interestingly, the m6A reader YTHDF1 plays an oncogenic role in cancer." (PMID 36551532, 2022). "Additionally, YTHDF1 expression differed in different immune subtypes of one cancer type." (PMID 34026603, 2021). "Therefore, YTHDF1 can be used as a new anticancer immunotherapy drug target or in combination with known immune checkpoint inhibitors to enhance immune infiltration and responses in cancers." (PMID 34026603, 2021). "Furthermore, low expression of YTHDF1 can reduce the sensitivity of cancer tissue to cisplatin was attributed to the Keap1-Nrf2-AKR1C1 axis (Kelch-like ECH-associated protein 1, NF-E2 p45-related factor 2 and antioxidant genes including aldo-keto reductases 1C1)." (PMID 33692959, 2021). "Thus, we hypothesized that YTHDF1, working as a potential pan-cancer biomarker or as a new immunotherapy target, may predict the immunotherapy response or achieve a promising therapeutic outcome, respectively." (PMID 34026603, 2021). "YTHDF1 may serve as a potential prognostic and immunological pan-cancer biomarker." (PMID 34026603, 2021). "Therefore, we speculated that hsa‐mir‐346 is a potential key upstream negative regulator of YTHDF1 and may be involved cancer treatment and prognosis." (PMID 32449290, 2020). "Therefore, we speculated that hsa‐miR‐346 is a potential key upstream negative regulator of YTHDF1 that may be related to cancer treatment and prognosis." (PMID 32449290, 2020). "Interestingly, YTHDF1 was recently reported to facilitate cancer stem cell properties." (PMID 33363211, 2020).
cancer (continued). "As proposed in our model, under normoxia conditions, constitutive activation of CDK-cyclin complexes, induced by YTHDF1 amplification, may contribute not only to uncontrolled cell proliferation but also to genomic and chromosomal instability, resulting in cancer progression." (PMID 31653849, 2019). "In addition, the m6A modified mRNA targets of YTHDF1 could be time- and cellular context- dependent, which leads to the differential functions of YTHDF1 in various cancers progression." (PMID 31653849, 2019). "Due to the frequent decreased expression of TEX2 in various cancers and lack of documented functions, we decided to further corroborate our hypothesis on the roles of YTHDF1, one of the m6A-specific mRNA binding and translation regulating proteins, in hypoxia tolerance and cancer progression." (PMID 31653849, 2019). "m6A modification by METTL3 stabilizes FBXO31 mRNA by binding to YTHDF1, which increases FBXO31 expression and promotes proteasome‐dependent degradation of sirtuin 2 (SIRT2), leading to cancer progression." (PMID 40448344, 2025). "Suppressing METTL3 and YTHDF1 expression decreases RPN2 levels, which inhibits this pathway and affects both cancer cell proliferation and chemotherapy efficacy." (PMID 39802639, 2025). "m6A regulators include writers (METTL3, METTL14, KIAA1429, and ZC3H13), erasers (ALKBH5 and FTO) and readers (YTHDF1/2/3, IGF2BP1/2/3), which are thought to play important roles in regulating cancer progression." (PMID 40774945, 2025). "Our study reveals that YTHDF1 boosts the translation efficiency of E3 ligase RNF7, which in turn accelerates the degradation of the cell cycle inhibitor p27, promoting malignant tumor cell growth in vitro and in vivo." (PMID 40251202, 2025). "Specifically, YTHDF1 and METTL3 have been reported to enhance myeloid-derived suppressor cell proliferation, which in turn inhibits CD8+ T cell function across various cancer types." (PMID 39995977, 2025). "Taken together, these results indicate that YTHDF1 is upregulated in NPC specimens relative to NPN tissues and is correlated with poor prognosis in advanced cancer and NPC patients." (PMID 41167308, 2025). "Beyond cancer, curcumin increased m6A on TRAF4 mRNA by inhibiting ALKBH5, which in turn enhanced YTHDF1-dependent TRAF4 translation and suppressed adipogenesis." (PMID 41322307, 2025). "Positive correlations between the expression of YTHDF3, YTHDF2, YTHDF1, and YTHDC1 and MIDN levels were detected in nearly all cancers." (PMID 40002690, 2025). "The MIDN level was correlated with several immune checkpoint genes, such as VEGFA, and RNA modification genes such as YTHDF1, YTHDF2, YTHDF3, and YTHDC1 in cancers." (PMID 40002690, 2025). "In our research, we proposed a novel mechanism of YTHDF1 post‐transcriptionally regulated UHRF1 level that promotes cell proliferation and cancer metastasis while inhibiting cell apoptosis." (PMID 38683130, 2024). "In lung adenocarcinoma, Wnt/β‐catenin signaling, along with YTHDF1, inhibits FTO expression and subsequently enhances c‐MYC expression, thereby promoting aerobic glycolysis and malignant behavior in cancer cells." (PMID 38721006, 2024). "In both cervical and liver cancers, m6A modification in the 5′‐UTR of PDK4 stabilises PDK4 via the YTHDF1/eEF‐2 complex and IGF2BP3, promoting glycolysis and cancer progression." (PMID 39135292, 2024). "In Transwell migration and invasion studies, siUHRF1 partially reversed cancer cell migration and invasion in NOZ cells after YTHDF1 overexpression." (PMID 38683130, 2024). "This impacts the recruitment of the reader YTHDF1 and subsequently affects MYC translation across various cancers." (PMID 38444581, 2024). "YTHDF1 depletion restores CD8 + T cell activity to inhibit cancer growth and promotes cancer cell death in combination with PD1 inhibitors." (PMID 39160604, 2024).